IL1B (interleukin 1 beta)
Diseases named in the same sentence as IL1B in open-access papers (continued):
Sharing a sentence is not in itself a finding about the gene and the disease.
myocardial infarction (continued). "In another study that the mice underwent permanent CAO, myocardial infarction promoted cardiac contractile dysfunction, and left ventricular myocardial fibrosis, and increased the amount of NLRP3, cleaved caspase-1, cleaved IL-1β, cleaved IL-18 in left ventricular tissue for four weeks." (PMID 36320147, 2022). "It suppresses p38 MAPK signaling pathway, and reduces arrhythmogenesis following myocardial infarction, and enhances cardiac function.It inhibits the expression of TLR4, MyD88, GM-CSF, IL-1β, TNF-α, and COX-2, and attenuates LPS-mediated TLR4-NF-κB pathway activation." (PMID 33868227, 2021). "Higher myocardial concentrations of IL-33, sST2, and IL-1β were detected in rats subjected to acute myocardial infarction, compared to the littermates without permanent left anterior descending artery ligation." (PMID 34884857, 2021). "In addition, a clinical study found that after revascularization of myocardial infarction, inflammatory factors in patients' serum including TNF-α, IL-1β, IL-6, and IL-8 were significantly increased." (PMID 34858542, 2021). "We measured and analyzed the immune cells including CD3+ T cells, CD19+ B cells, Ly6G+ neutrophils, F4/80+ macrophages, and inflammatory factors such as IL-1b, Il-6, IL-12, TNFa, and MCP-1 in the heart tissue from different groups at day 7 after myocardial infarction." (PMID 32641103, 2020). "Interestingly, IL-1β and TNF-α act coordinately to increase AT1 receptor density in post-myocardial infarction, thus suggesting a vicious cycle of Ang II-induced myocardial cytokine production and cytokine-induced increase in Ang II activity." (PMID 30959745, 2019). "Recently, inhibition of IL-1β and subsequent reduction of inflammation (without modification of lipid levels) in patients with previous episodes of myocardial infarction was found to reduce recurrent cardiovascular events." (PMID 29213245, 2017). "Companying with same dose of SalB or Rg1 only, SalB-Rg1 showed more significant effects on down-regulation of myocardial infarct size, maintenance of myocardium structure, improvement on cardiac function, decrease of cytokine secretion including TNF-α, IL-1β, RANTES and sVCAM-1." (PMID 26280455, 2015). "In both diabetic and non-diabetic rats with heart failure following a myocardial infarction, the administration of the anti-IL-1β antibody gevokizumab reduced the ventricular dimensions and improved its function (measured by echocardiography), decreasing hypertrophy and fibrosis." (PMID 40360833, 2025). "Importantly, cytokines, such as IL-1β, IL-6, and IL-8, are known to potentiate both primary hemostasis (formation of platelet plugs) and secondary hemostasis (the coagulation cascade), which, in the setting of CAD, can explain myocardial infarction." (PMID 41156763, 2025). "HUMSCs-derived exosomes loaded with a miR-29b mimic suppressed expression of interleukin 1β (IL-1β)/-6, tumor necrosis factor alpha (TNF-α), and inducible nitric oxide synthase (iNOS) and reduced myocardial fibrosis when delivered through a microneedle patch to a myocardial infarction." (PMID 40676634, 2025). "In a myocardial infarction (MI) mouse model induced by left anterior descending (LAD) coronary artery ligation, ALA administration reduced infarct size and the serum levels of IL-1β, TNF-α, and creatine kinase-myocardial band (CKMB)." (PMID 40699721, 2025). "Inhibition of IL-1β by canakinumab, reduced the rates of nonfatal myocardial infarction, nonfatal stroke, or cardiovascular death compared with placebo in patients with prior myocardial infarction and high sensitivity CRP ≥ 2 mg/L, with consistent effects regardless of DM." (PMID 37735399, 2023). "For example, the Canakinumab Anti-Inflammatory Thrombosis Outcomes Study investigated whether treatment with canakinumab, a monoclonal antibody that specifically neutralises IL-1b, would benefit people with CRP > 2.0 mg/L and a history of myocardial infarction." (PMID 37953258, 2023).
myocardial infarction (continued). "Interestingly, APAF1 and IRAK3 expression correlated negatively with NK cell abundance in both acute myocardial infarction and ischemic stroke, whereas ATM, CAPN1, IL1B, IL1R1, PRKACA, PRKACB, and TNFRSF1A correlated negatively with NK cell abundance in acute myocardial infarction." (PMID 35432334, 2022). "IL-1α and IL-1β are both agonists of the IL1R; IL-1α is released by necrotic cardiomyocytes and functions as an alarm signal, triggering a postinfarction inflammatory reaction, while IL-1β is produced by the leukocytes invading the infarct area after myocardial infarction." (PMID 33513892, 2021). "Importantly, pro-inflammatory cytokine levels are elevated in the myocardium following myocardial infarction (including TNF-α, IL-1β, and IL-6), producing electrophysiological changes, suggesting that the persistent existence of inflammation is an important contributor to arrhythmia." (PMID 32116751, 2020). "Thus, these authors hypothesized that IL-1β might induce BNP secretion and cardiac hypertrophy in acute myocardial infarction or heart failure." (PMID 32393333, 2020). "Recently, the first results of CANTOS (Canakinumab Anti-Inflammatory Thrombosis Outcome Study) showed that a monoclonal antibody targeting IL-1β in post-myocardial infarction patients reduces non-fatal myocardial infarction, non-fatal stroke, and cardiovascular death." (PMID 31052244, 2019). "In the CANTOS trial, a multiyear study of >10,000 patients with previous myocardial infarction (MI) and high CRP levels, the anti-IL-1β antibody canakinumab provided dose-dependent reductions in CRP level and reduced the incidence of cardiovascular death." (PMID 30279971, 2018). "For example, typical signs of pyroptosis such as upregulation of caspase-1 and interleukin 1β (IL-1β) in myocardial infarction (MI) have been reported, suggesting that modulation of pyroptosis may be a viable therapeutic target for alleviating selective cardiovascular diseases such as MI." (PMID 26491223, 2015). "In this study, patients with a history of myocardial infarction (MI) and elevated levels of high-sensitivity C-reactive protein (hs-CRP) (≥2 mg/dl) were randomly assigned to receive either canakinumab [an interleukin-1β (IL-1β) monoclonal antibody] or placebo." (PMID 38993522, 2024). "However, more evidence suggested that mechanism by which the NLRP3 inflammasome induces myocardial infarction expansion and cardiomyocyte death may be through pyroptosis rather than IL-1β production." (PMID 37957640, 2023). "Importantly, the IL-1β-neutralizing antibody canakinumab has demonstrated considerable clinical benefits, reducing recurrent cardiovascular events by 17% in patients with a previous myocardial infarction (CANTOS trial), independent of the lipid level." (PMID 37894840, 2023). "CANTOS enrolled 10,061 participants with a history of myocardial infarction (MI), optimized LDL-C, and hsCRP ≥ 2 mg/L and randomized them to optimal medical therapy (OMT) plus placebo vs. OMT plus canakinumab, a fully human monoclonal antibody targeted to interleukin-1β (IL-1β)." (PMID 32478100, 2020). "Treatment with an IL-1β-antibody did not affect inflammasome formation in myocardial tissue at 72 hours after CAO but inhibited cardiomyocyte apoptosis, limited left ventricular enlargement and improved systolic and diastolic cardiac function 7, 28 and 70 days after myocardial infarction." (PMID 36320147, 2022).
Alzheimer disease (352 papers, 2005 to 2026). A progressive, neurodegenerative disease characterized by loss of function and death of nerve cells in several areas of the brain leading to loss of cognitive function such as memory and language. "IL-1β remained significant for associations with total brain, total white and gray volumes, hippocampal, and Alzheimer’s disease signature regions." (PMID 39883521, 2025). "Interleukin (IL)-1β is a key cytokine involved in the inflammatory response in a variety of diseases, and it has been linked to Alzheimer’s disease (AD) pathology." (PMID 39859545, 2025). "NLRP3 inflammasome-dependent caspase-1 activation is an important pathway related to IL-1β release and has been implicated in the pathophysiology of neurological diseases, including Parkinson’s disease, Alzheimer’s disease, multiple sclerosis, and epilepsy." (PMID 38218765, 2024). "Activation of NLRP3-containing inflammasome, which is responsible for IL-1β maturation, has been shown to contribute to Alzheimer’s disease (AD)-associated pathogenesis in both APP- and tau-transgenic mice." (PMID 39539344, 2024). "For this reason, it is possible that the inflammasome signaling pathway is a factor in the presentation of Alzheimer’s disease (AD), as increased IL1β was associated with the response to beta-amyloid (Aβ) deposition." (PMID 37505534, 2023). "IL-1β is the main pro-inflammatory cytokine associated with neuroinflammation in the course of Alzheimer’s disease." (PMID 36045741, 2022). "Enhanced NLRP3 inflammasome-mediated IL-1β secretion in microglia is associated with the progression of Alzheimer’s disease by reducing the phagocytosis of Aβ from microglia." (PMID 35514993, 2022). "Primary microglia stimulation in vitro by fibrillar Aβ activates the production of NLRP3 inflammasome, caspase-1, causing the increased secretion of IL-1β in the animal models of Alzheimer’s disease." (PMID 36009120, 2022). "Alzheimer’s disease patients with raised serum levels of pro-inflammatory cytokines IL-1β and TNF-α are indeed at increased risk of subsequent cognitive decline." (PMID 33723589, 2021). "Polymorphisms in the NLRP1 gene are associated with Alzheimer’s disease and multiple sclerosis, the latter resulting in an increase of IL-1β expression in peripheral blood mononuclear cells isolated from patients carrying these polymorphisms." (PMID 31892810, 2019). "The inflammatory score composited of blood IL-10 and other cytokines including TNF-α, IL-23, and IL-1β was negatively associated with lower FA in patients with Alzheimer’s disease." (PMID 30792621, 2019). "We recently showed that IL-1b and IL-6 DNA methylation is modulated in the brain of Alzheimer’s disease patients, and that IL-1b expression is associated to DNA methylation in the brain of patients with tuberous sclerosis complex." (PMID 28954414, 2017). "A chronic inflammatory response associated with Aβ and IL-1β is responsible for the pathology of Alzheimer’s disease." (PMID 25871293, 2015). "Similar results with increased IL1β resulting from loss of Cx3cr1 were shown in two Alzheimer's disease mouse models and other CNS diseases." (PMID 25987130, 2015). "Conversely, murine models of bacterial meningitis as well as a number of chronic neurodegenerative diseases including amyotrophic lateral sclerosis (ALS) and Alzheimer’s disease (AD) have linked inflammasome-dependent IL-1β release to the promotion of disease." (PMID 24886384, 2014). "IL-1β overexpression has been implicated as factor in the initiation and progression of Alzheimer's disease." (PMID 22312330, 2012). "We showed that the IL1A -889 T/T and IL1B +3954 T/T genotypes mark increased risk for late-onset Alzheimer's disease (LOAD) in an Australian cohort." (PMID 18715507, 2008). "The other polymorphism in IL-1β (at position +3953 in exon 5) has shown an association with the risk for Alzheimer's disease." (PMID 17563722, 2007).
Alzheimer disease (continued). "A C/T polymorphism at position -511 of the IL-1β gene in the promoter region has been reported to be associated with Alzheimer's disease, with the IL-1β(-511) T allele polymorphism found to increase the risk for late-onset Alzheimer's disease." (PMID 17563722, 2007). "The interleukin-1β (IL-1β; -511) and IL-1β (+3953) polymorphisms were found to increase risk with Alzheimer's disease." (PMID 17563722, 2007). "Microglia cells activation and release of pro-inflammatory cytokines such as TNF-α and IL-1β, which can cause neuro-inflammation by forming amyloid-beta plaque and might trigger pathogenesis in Alzheimer's disease." (PMID 37113148, 2023). "It was reported that increased inflammatory response was implicated in neurodegenerative disorders, including Alzheimer’s disease, PD and amyotrophic lateral sclerosis, and a meta-analysis demonstrated that the expression of IL-1β, IL-6, and TGF-β were upregulated in PD." (PMID 34967706, 2022). "Previous study has reported that caspase-1/IL-1β is closely associated with Alzheimer's disease." (PMID 33509083, 2021). "In addition, inhibition of p38-MAPK activity can revert the loss of synaptophysin induced by IL-1β in rat primary cortical neuronal cultures and in an animal model of Alzheimer’s disease." (PMID 28288671, 2017). "Water-soluble chitosan inhibits the production of pro-inflammatory cytokine in human astrocytoma cells activated by Aβ and IL-1β and may reduce and delay the pathological events associated with Alzheimer’s disease." (PMID 25871293, 2015). "Accordingly, Calogero Caruso (University of Palermo, Italy) reviewed the reports indicating an association between the risk of Alzheimer Disease (AD) and polymorphisms of genes encoding inflammatory mediators, such as IL-1β, IL-6, IL-10 and TNF-α, as well as the possible involvement of Zn." (PMID 17883856, 2007). "In addition, P2X7 activation on microglia has been implicated in the pathogenesis of experimental autoimmune encephalomyelitis (EAE), Alzheimer disease (AD), and stroke, which are often associated with an increased release of IL-1β." (PMID 36299894, 2022). "Given the potential similarities in cellular events leading to neurodegeneration between Alzheimer's disease and glaucoma, we hypothesized that the IL-1β (-511) and IL-1β (+3953) polymorphisms, because of the effect on IL-1 protein expression, may predispose affected individuals to glaucoma." (PMID 17563722, 2007). "In Alzheimer’s disease models, IL-1β expression is upregulated following Aβ deposition and exacerbates neuroinflammation by amplifying glial reactivity and cytokine release, thereby accelerating disease progression." (PMID 40934003, 2025). "In neurodegenerative diseases such as Alzheimer’s disease (AD), activated microglia initiate neuroinflammation by releasing cytokines (IL-1β, IL-6, and TNF-α), leading to neuronal damage, Aβ plaque accumulation, and tau hyperphosphorylation." (PMID 40242775, 2025). "When the amyloid precursor protein/presenilin 1 mouse model of Alzheimer’s disease (AD) was subjected to a secondary inflammatory challenge with interleukin-1β (IL-1β), primed astrocytes developed exaggerated chemokine responses." (PMID 39463449, 2025). "Interleukin (IL)-1β is a pro-inflammatory cytokine whose levels are increased in the brains of Alzheimer’s disease (AD) patients." (PMID 39859545, 2025). "Recent studies utilizing animal models have shown the capacities of anti-TNFα and anti-IL-1β in attenuating neurological deficits in Alzheimer’s disease, Parkinson’s disease, and ischemic stroke." (PMID 40338234, 2025). "Conversely, IL-1β can lead to activation of multiple signaling cascades that are known to have the potential to give rise to the development of Alzheimer’s disease, Parkinson’s disease, multiple sclerosis, and epilepsy." (PMID 40725140, 2025).
Alzheimer disease (continued). "Elevated levels of IL-1β, IL-6, MCP-1, and TNF-α, alongside reduced IL-8 and IL-10 levels, suggest a robust inflammatory response associated with Alzheimer’s disease." (PMID 40711681, 2025). "AVE0991 treatment in the APP/PS1 double-transgenic mouse model of Alzheimer’s disease suppressed astrocyte-mediated inflammation by downregulating the expression profile of IL-1β, IL-6, and TNF-α in the brain cortex." (PMID 40565247, 2025). "It proved that STING, NLRP3 or IL‐1β gene had important roles in the progression of Alzheimer's disease." (PMID 37528567, 2024). "More recently, it was reported that treatment with Tan IIA reduced the expression of proinflammatory cytokines such as NF-κB, TNF-α, IL-6, and IL-1β in Alzheimer's disease model." (PMID 39687171, 2024). "Cathepsin B (CatB) is thought to be essential for the induction of Porphyromonas gingivalis lipopolysaccharide (Pg LPS)-induced Alzheimer’s disease-like pathologies in mice, including interleukin-1β (IL-1β) production and cognitive decline." (PMID 38334675, 2024). "In a transgenic model for Alzheimer’s disease, sustained hippocampal IL-1β overexpression ameliorated β-amyloid plaques size and frequency." (PMID 38389906, 2024). "In the cerebrospinal fluid of Alzheimer's disease patients, abnormally elevated levels of IL-1β and IL-18 were detected." (PMID 38317229, 2024). "For example, in Alzheimer’s disease, primed microglia produce elevated levels of IL-1β and TNF-α upon encountering amyloid plaques, intensifying neuroinflammation and accelerating neuronal damage." (PMID 39769374, 2024). "Others have reported that AD-16 was able to reduce IL-1β expression induced by LPS in vivo, restore IL-4 and IL-6 levels in a mouse model of Alzheimer’s disease, and reduce IL-1β and TNF-α levels in the brain of ischemic mice." (PMID 39736920, 2024). "The NLRP3 inflammasome is also a key element in Alzheimer’s disease (AD); its activation induces increased synthesis of pro-IL-1β and pro-IL-18 and activates caspase-1." (PMID 38928621, 2024). "Research has demonstrated heightened levels of IL-1β and IL-18 in the cerebrospinal fluid, brain tissue, and plasma of individuals affected by CNS infections, brain injuries, Alzheimer’s disease (AD), and multiple sclerosis (MS)." (PMID 38259497, 2023). "In an Alzheimer’s disease model with transgenic Tg2576 mice, reactive astrocytes surrounding Aβ plaques expressed high levels of interleukin-1β (IL-1β)." (PMID 37921870, 2023). "High IL-1β and IL-18 levels were detected in patients with CNS infection, brain injuries, Alzheimer’s disease, and multiple sclerosis." (PMID 36675440, 2023). "An in vitro study in which neurons and astrocytes were isolated from mice with Alzheimer’s disease (AD) showed that knockout of the MMP-24 gene significantly reduced IL-1β and β-amyloid (Aβ) in cells." (PMID 36979351, 2023). "In cerebral hypoperfusion and Alzheimer's disease models, activated glia was shown to release proinflammatory factors such as IL-1β, IL-6, TNF-α, COX-2, and iNOS, promoting further neuronal degeneration in the hippocampus." (PMID 37064799, 2023). "In individuals with Alzheimer’s disease, the brain exhibits elevated levels of IL-1β and oxygenated cholesterol molecules (oxysterols)." (PMID 37894967, 2023). "Persistent low-grade inflammation in the brain has been reported to exacerbate neurodegenerative pathologies, including PD and Alzheimer diseases, with pro-inflammatory cytokines such as IL-1β and IL-6 considered key drivers." (PMID 38110963, 2023). "Neuroinflammation is a key player in Alzheimer’s disease (AD), with the active participation of proinflammatory cytokines such as IL-1β and TNF-α, which promote neuronal and synaptic disorders." (PMID 37237873, 2023). "In Alzheimer`s disease, high levels of IL-1β were detected in microglial cells surrounding Aβ plaques and in the CSF of patients suffering from the disease, suggesting that this cytokine promoted neurodegeneration." (PMID 34216357, 2022).